BCL6 (BCL6 transcription repressor)
Diseases named in the same sentence as BCL6 in open-access papers (continued):
Sharing a sentence is not in itself a finding about the gene and the disease.
ovarian carcinoma (continued). "And in ovarian carcinoma, BCL6 facilitated the proliferation and invasion of tumor cells while its expression level tightly associated with the Federation of Gynecology and Obstetrics (FIGO) stage." (PMID 30420967, 2018). "As a first attempt, our study demonstrates that targeting BCL6 may be an effective approach to treat ovarian cancer and that WK369 has the potential to be used as a candidate therapeutic agent for ovarian cancer." (PMID 38169532, 2024). "Finally, a mechanism involving direct stabilization of the BCL6 protein by the tumorigenic (lncRNA) 00152 has been identified in ovarian cancer." (PMID 39456751, 2024). "Moreover, we showed that NAC1 and BCL6 are coordinately upregulated in ovarian cancer, and NAC1 plays an important role in attenuating BCL6 autoregulation." (PMID 32412910, 2020). "In addition, we found a significant overlap of NAC1- and BCL6-regulated genes in OVCAR-5 cells, suggesting a transcription collaboration of NAC1 and BCL6 in ovarian cancer cells." (PMID 32412910, 2020). "Moreover, in ovarian cancer, BCL6 expression is closely correlated with FIGO staging, lymph node metastasis and recurrence and has been recently described as a negative prognostic factor." (PMID 32412910, 2020). "The similar observations were made in the cells expressing either NAC1 or BCL6 supporting that the NAC1/BCL6 transcription regulation complex may be responsible for promoting development of ovarian cancer." (PMID 32412910, 2020). "Importantly, we observed a strong correlation between the expression of NACC1 and BCL6 transcripts in the ovarian cancer cell lines tested (R2=0.7025; P=0.0185)." (PMID 32412910, 2020). "Moreover, NAC1 and BCL6 protein expression in ovarian cancer samples showed a similar pattern (R2=0.31, P=0.027; graph not shown)." (PMID 32412910, 2020). "However, the role of targeting BCL6 in ovarian cancer remains elusive." (PMID 38169532, 2024). "Therefore, we speculated that BCL6 inhibition through WK369 activating the expression of these genes to suppress ovarian cancer growth and metastasis." (PMID 38169532, 2024). "However, BCL6 targeted therapy in ovarian cancer is rarely reported." (PMID 38169532, 2024). "Even broader roles for NAC1 and BCL6 might exist in ovarian cancer, as ingenuity pathway analysis has revealed the upregulation of IL-17, IL-8, and IL-6 signaling pathways, which were reported to be correlated with novel functions in driving tumor growth and stemness." (PMID 32412910, 2020). "Therefore, BCL6 may be an attractive therapeutic target for ovarian cancer." (PMID 38169532, 2024). "The utility of BCL6 inhibitors extends to solid tumors, with WK369 being shown to inhibit the growth and metastasis of ovarian cancer." (PMID 39456751, 2024). "Meanwhile, WK369 showed better anti-ovarian cancer activity and anti-DLBCL cancer cell activity than BCL6 inhibitors FX1 and WK500B." (PMID 38169532, 2024). "Therefore, it is speculated that tumors can be synergistically inhibited by combining BCL6 inhibitors with chemotherapy drugs, which may provide some treatment options for patients with drug-resistant ovarian cancer or patients who are insensitive to chemotherapy drugs." (PMID 38169532, 2024). "All of these observations support a coordinate up-regulation of NAC1 and BCL6, and underscore the importance of the NAC1/BCL6 complex in ovarian cancer." (PMID 32412910, 2020). "Nevertheless, all of these inhibitors are against DLBCL, BCL6 targeted therapy in ovarian cancer has not been explored." (PMID 38169532, 2024). "Furthermore, BCL6-expressing B cells and CD21-positive follicular dendritic cells have been shown to be concentrated in TLS in ovarian cancer." (PMID 39620224, 2024). "In ovarian cancer, miR‐339 inhibited the tumor progress by directly regulating NACC1 and Bcl6 while miR‐339 regulated the metastasis of colorectal cancer via targeting PRL‐1.23, 24 LncRNA RP11‐81H3.2 might function as a ceRNA and sponge the miR‐339." (PMID 32052594, 2020).
ovarian carcinoma (continued). "Our observation that NAC1 and BCL6 activate FOXQ1 promoter activity via a positive, cooperative mechanism suggest that these molecules may be coordinately regulated in ovarian cancer." (PMID 32412910, 2020). "To test this hypothesis, we examined the expression of NAC1 and BCL6 transcripts in a panel of 7 ovarian cancer cell lines and assessed NAC1 and BCL6 protein expression in 51 high-grade serous ovarian adenocarcinoma samples." (PMID 32412910, 2020). "Thus, as a BCL6 inhibitor, WK369 provides a potential approach for the treatment of ovarian cancer." (PMID 38169532, 2024).
non-Hodgkin lymphoma (20 papers, 1997 to 2025). Distinct from Hodgkin lymphoma both morphologically and biologically, non-Hodgkin lymphoma (NHL) is characterized by the absence of Reed-Sternberg cells, can occur at any age, and usually presents as a localized or generalized lymphadenopathy associated with fever and weight loss. "For example, APM-1 inhibits the growth of cervical carcinoma, and the human BCL-6 and promyelocytic leukemia zinc finger proteins are causally involved in non-Hodgkin's lymphoma and acute promyelocytic leukemia, respectively." (PMID 19508730, 2009). "The protein was originally cloned as a fusion transcript with LAZ3/BCL6 in a non-Hodgkin lymphoma cell line and has since been found to be mutated or translocated in a number of human cancers." (PMID 18823547, 2008). "The B cell lymphoma 6 (BCL6, also called BCL6A) protein was first identified as the product of a gene involved in chromosomal translocations in the context of non-Hodgkin’s lymphoma (NHL)." (PMID 39456751, 2024). "Selective targeting of BCL6 is endowed with great potential in the fight against different diseases, especially non-Hodgkin lymphomas." (PMID 36473934, 2022). "The peptide inhibitor 79-6 has been developed to block Bcl-6 activity in non-Hodgkin lymphoma patients with aberrant Bcl-6 expression." (PMID 27880939, 2017). "Of note, Bcl-6 was originally discovered in non-Hodgkin lymphomas where chromosomal translocations led to aberrant Bcl-6 expression." (PMID 27880939, 2017). "The protein was first discovered as a fusion transcript with the transcriptional repressor LAZ3/BCL6 in Non Hodgkin lymphoma cells." (PMID 20738848, 2010). "They had previously shown that the zinc finger protein and translational repressor LAZ3/BCL6 is disrupted in non-Hodgkin lymphomas." (PMID 18823547, 2008). "Finally, two novel agents, BMS-986458, a BCL6 degrading compound, and ARV-393, a BCL6 targeting PROTAC, are currently under clinical investigation to assess their safety and efficacy in targeting BCL6 in relapsed/refractory non-hodgkin lymphoma patients." (PMID 41246349, 2025). "BCL6 has already been suggested as a promising drug target for non-Hodgkin lymphomas." (PMID 36473934, 2022). "The most frequently determined markers in the non-Hodgkin lymphoma are CD20, CD3, CD5, CD10, BCL6, BCL2, Ki-67, MYC, and cyclin D1." (PMID 40142344, 2025). "It has been shown to be overexpressed in most of the human non-Hodgkin lymphoma cases (NHL) and commonly in conjunction with BCL6 (ZBTB27)." (PMID 31823818, 2019). "SC-1, a follicular non-Hodgkin lymphoma subtype harboring chromosomal rearrangements in MYC, BCL6 and BCL2, was among the cell lines found to be most sensitive to (−)-CR-1-31-b and CMLD011580." (PMID 30718665, 2019).
glioblastoma (16 papers, 2017 to 2025). The most malignant astrocytic tumor (WHO grade IV). "Despite the reported association between BCL6 and apoptosis in glioblastoma, and the significant increase in apoptosis gene set expression, none of the inhibitory approaches induced widespread apoptosis." (PMID 32320427, 2020). "In our research, we further confirmed the high level of BCL6 was associated with a range of malignant characteristics in glioblastoma cells, including proliferation, migration, and invasion." (PMID 30420967, 2018). "We then assessed KLF6 and BCL6 associations with survival in 406 patients with glioblastoma." (PMID 28166199, 2017). "When BCL6 expression or activity was reduced in these lines, increased apoptosis and a profound loss of proliferation was observed, consistent with gene expression signatures suggestive of anti-apoptotic and pro-survival signaling role for BCL6 in glioblastoma." (PMID 32320427, 2020). "In addition, we explored the underlying molecular events of BCL6 action in glioblastoma cells." (PMID 30420967, 2018). "BCL6 is reportedly upregulated in glioblastoma and gastric, ovarian, and non-small cell lung cancers, and its expression is associated with malignant features, including proliferation, invasivity, migratory activity, survival, and therapeutic resistance." (PMID 40070829, 2025). "At very low dose, down to 15 nM, doxorubicin had little direct impact on viability of glioblastoma cell lines, but led to significant induction of BCL6 over 24 hours." (PMID 32320427, 2020). "Further, treatment with the standard therapies for glioblastoma—ionizing radiation and temozolomide—both induced BCL6 expression in vitro, and an in vivo orthotopic animal model of glioblastoma." (PMID 32320427, 2020). "NZG-0804, another primary glioblastoma line, had high levels of nuclear BCL6 in about half of all cells, with cytoplasmic BCL6 also present, while the primary line NZG-1003 had no basal expression." (PMID 32320427, 2020). "In this study, we assessed the spectrum of BCL6 protein in glioblastoma survival and therapy resistance, and demonstrated a key role for BCL6 in survival of glioblastoma cells in vitro after DNA damage." (PMID 32320427, 2020). "We believe that addition of BCL6 inhibition to the standard protocols of chemo-radiation has real potential to improve the outcome for people with glioblastoma." (PMID 32320427, 2020). "The glioblastoma cell lines were treated with temozolomide, ionizing radiation and doxorubicin, then BCL6 protein level and sub-cellular localization assessed by both western blot and immunofluorescence microscopy." (PMID 32320427, 2020). "Consistent with prior reports, the apoptosis pathway was significantly up-regulated, confirming that BCL6 does indeed have anti-apoptotic activity in glioblastoma." (PMID 32320427, 2020). "This makes BCL6 an excellent therapeutic target in glioblastoma—by increasing sensitivity to standard DNA damaging therapy, BCL6 inhibitors have real potential to improve the outcome for people with this disease." (PMID 32320427, 2020). "Consistent with reported poor apoptosis in glioblastoma, the total number of cells with active caspase-3 was low, but reproducibly increased from control- to BCL6-siRNA treated cells, 2-fold for NZG-1003 and T98G, and 7-fold in LN18." (PMID 32320427, 2020). "We attempted to create isogenic pairs of glioblastoma cell lines, by knock-out of the BCL6 locus in LN18 and U87-MG cells using nuclease-mediated genome editing." (PMID 32320427, 2020). "In glioblastoma cells, knockdown of the BCL6 gene inhibited malignant phenotype and enhanced sensitivity to temozolomide through inhibition of the AKT pathway." (PMID 31903146, 2020). "We compared the expression and subcellular localisation of BCL6 in a panel of glioblastoma cell lines, by immunofluorescence microscopy." (PMID 32320427, 2020).
glioblastoma (continued). "BCL6 inhibition in glioblastoma is highly feasible—several inhibitors, both peptide and small molecule, have been developed for BCL6, including some that should pass through the blood-brain barrier and accumulate in the brain." (PMID 32320427, 2020). "The localization of BCL6 in glioblastoma was particularly interesting—in many cases, it appeared to localize to perivascular regions of glioblastoma." (PMID 32320427, 2020). "Together these data demonstrate that BCL6 is an active transcription factor in glioblastoma, that it drives survival of cells, and that it increased with DNA damage, which increased the survival rate of therapy-treated cells." (PMID 32320427, 2020). "All three co-repressors were expressed in all of the glioblastoma cell lines used in this study, suggesting that glioblastoma cells have the necessary machinery intact for BCL6 to repress transcription." (PMID 32320427, 2020). "Here, we identified a series of pathways driving cell survival that are regulated by BCL6, and confirmed that BCL6 was essential for proliferation and survival of glioblastoma." (PMID 32320427, 2020). "As translocation of BCL6 frequently occurred in high-grade glioblastoma, the expression of BCL6 had higher levels in Grades III and IV tumors than lower grade glioma tissues." (PMID 30420967, 2018). "Knockdown of BCL6 expression reduced the proliferation, migration, and invasion of glioblastoma cells." (PMID 30420967, 2018). "RT-PCR and Western blot were used to detect the expression of BCL6 mRNA and protein in tissues and glioblastoma cell lines." (PMID 30420967, 2018). "The expression of BCL6 was knockdown in two glioblastoma cell lines (U87 and U251) using BCL6 shRNA." (PMID 30420967, 2018). "In this study, we identified the high expression of BCL6 in glioma tissues and cell lines, and then we investigated the role of BCL6 expression in regulation of glioblastoma proliferation, migration, invasion, and chemosensitivity in vitro." (PMID 30420967, 2018). "Parallel to tissues, the six glioblastoma cell lines displayed a higher level of BCL6 in mRNA compared with normal brain tissues." (PMID 30420967, 2018). "The expression of BCL6 was higher in glioma tissues and glioblastoma cell lines than normal tissues." (PMID 30420967, 2018). "Importantly, in GBM BCL6 expression can be found associated with defects in apoptosis—for example, BCL6 and the BCL6 target gene EP300 are among anti-apoptosis genes in a signature of survival in primary glioblastoma." (PMID 32320427, 2020). "Importantly, we demonstrated that BCL6 is induced by the therapies used to treat glioblastoma, and that the pro-survival activity of ‘therapy-induced’ BCL6 helps drive the intrinsic resistance to therapy observed in this disease." (PMID 32320427, 2020). "Also supporting our current findings, it has been shown that BCL6 depletion in glioblastoma cells sensitized these cells to the EGFR-TKI erlotinib." (PMID 32234966, 2020). "Finally, BCL6 protein was also observed in a subset of glioblastoma, where it was correlated with increased expression of the Axl kinase." (PMID 32320427, 2020). "Again using multiple modes of inhibition, we clearly demonstrated that BCL6 is very important in glioblastoma cell survival—BCL6 inhibition using the small molecule FX1 at 40 μM stopped all long-term proliferation, and even at 25 μM there was significant suppression of colony formation." (PMID 32320427, 2020). "In order to understand whether therapy-induced BCL6 is a transcriptional repressor in glioblastoma, we used the classic BCL6 responsive luciferase reporter system." (PMID 32320427, 2020).
glioblastoma (continued). "Defects in the apoptotic and cell death pathways are critical in the survival of glioblastoma and resistance to treatment, and we hypothesized that these defects could be driven by BCL6 activity in glioblastoma, based on the following lines of evidence." (PMID 32320427, 2020). "And BCL6 was expressed to different in glioblastoma cell lines." (PMID 30420967, 2018). "Moreover, knockdown of BCL6 changed expression of proteins related to malignant behaviors of glioblastoma cells." (PMID 30420967, 2018). "Interestingly, the effect of total BCL6 reduction (siRNA) was equivalent to specifically blocking protein-protein interaction at the BTB pocket (RI-BPI), suggesting that the BTB pocket may be a key mediator of BCL6 activity in glioblastoma." (PMID 32320427, 2020). "These could also contribute to the protective effect of BCL6 in glioblastoma." (PMID 32320427, 2020). "This reinforced the hypothesis that BCL6 is essential for survival of glioblastoma cells." (PMID 32320427, 2020). "The data presented here strongly support the hypothesis that BCL6 drives survival in glioblastoma." (PMID 32320427, 2020). "Also, reduction of BCL6 increases chemosensitivity of glioblastoma to temozolomide." (PMID 30420967, 2018). "Over-expression of BCL6 in both LN18 and U87-MG cells specifically led to the suppression of transcription driven by a BCL6 responsive element (pBCL64-tk-LUC), confirming that glioblastoma cells are indeed competent for transcriptional repression by BCL6." (PMID 32320427, 2020). "The nature of the relationship between BCL6 and MGMT expression in glioblastoma is unclear, but could provide a double hit of therapy resistance—MGMT would repair the TMZ-mediated damage, while BCL6 induced by radiotherapy and TMZ would enhance survival." (PMID 32320427, 2020). "Whether BCL6 similarly directly activates transcription in glioblastoma has not yet been determined." (PMID 32320427, 2020). "Similarly there was also no overt relationship between BCL6 level and IDH1 mutation, another mutation more common in secondary glioblastoma." (PMID 32320427, 2020). "Together, these data suggest that BCL6 induced by therapy in glioblastoma is transcriptionally active, but may not have the classic ‘transcriptional repressor’ activity observed in B cells." (PMID 32320427, 2020). "However, the number of apoptotic cells was small, indicating that while BCL6 has some role in preventing apoptosis, supported by previous observations, it is not entirely responsible for poor apoptosis in glioblastoma." (PMID 32320427, 2020).